SNORD87 (small nucleolar RNA, C/D box 87)
Synonyms: HBII-276; U87
Gene: Small nucleolar RNA gene on chromosome 8 (66,922,467 to 66,922,555, reverse strand). Ensembl gene ENSG00000254341.
Gene Ontology:
Biological process: RNA processing
Cellular component: nucleolus
Homologues: Orthologues: chimpanzee SNORD87 (99% identical), macaque SNORD87 (98% identical), pig SNORD87 (93% identical), rabbit SNORD87 (93% identical), guinea pig SNORD87 (89% identical), mouse Snord87 (87% identical), rat Snord87 (85% identical).